RGS21 (regulator of G protein signaling 21)
Description:
Inhibits signal transduction by increasing the GTPase activity of G protein alpha subunits thereby driving them into their inactive GDP-bound form.
Tractability: Antibody: its Gene Ontology location is reachable by antibodies, with medium confidence.
Gene: Protein-coding gene on chromosome 1 (192,316,992 to 192,367,285, forward strand). Ensembl gene ENSG00000253148.
Pathways (Reactome):
Signal Transduction: G alpha (i) signalling events; G alpha (q) signalling events
Gene Ontology:
Molecular function: GTPase activity
Biological process: G protein-coupled receptor signaling pathway; negative regulation of G protein-coupled receptor signaling pathway; sensory perception of bitter taste; sensory perception of sweet taste; sensory perception of umami taste; transmission of nerve impulse
Cellular component: cytoplasmic side of plasma membrane; plasma membrane
Genetic constraint (gnomAD): Loss-of-function variants: 1 observed, 1.3 expected, observed/expected ratio (o/e) 0.77, 90% interval 0.23 to 1.86. That is too few expected variants to judge how well the gene tolerates losing a copy. Missense variants: 37 observed, 36.42 expected, observed/expected ratio (o/e) 1.02, 90% interval 0.78 to 1.34. Synonymous variants: 8 observed, 11.67 expected, observed/expected ratio (o/e) 0.69, 90% interval 0.4 to 1.24.
Homologues: Orthologues: chimpanzee RGS21 (99% identical), macaque RGS21 (95% identical), dog RGS21 (92% identical), rabbit RGS21 (91% identical), mouse Rgs21 (88% identical), pig RGS21 (88% identical), guinea pig RGS21 (86% identical), rat Rgs21 (86% identical), tropical clawed frog RGS21 (53% identical), zebrafish si:ch211-196h16.12 (41% identical). Paralogues in human: RGS1 (54% identical), RGS2 (53% identical), RGS18 (47% identical), RGS3 (47% identical), RGS5 (47% identical), RGS4 (46% identical), RGS8 (45% identical), RGS16 (44% identical), RGS13 (40% identical), RGS17 (40% identical), RGS20 (39% identical), RGS9 (36% identical), and 11 more.
Diseases named in the same sentence as RGS21 in open-access papers:
RGS21 is named in the same sentence as 6 diseases in open-access papers, as found by Europe PMC text mining. Sharing a sentence is not in itself a finding about the gene and the disease. The quoted sentences say what the papers report.
celiac disease (2 papers, 2016 to 2024). An autoimmune genetic disorder with an unknown pattern of inheritance that primarily affects the digestive tract. "On the other hand, association evidence for RGS21, IL18R1, PLEK, CCR9, TAGAP was only found for celiac disease." (PMID 27015091, 2016). "We found 54 single-nucleotide polymorphisms (SNPs) in 5 genes associated with celiac disease (TAGAP, IL18R1, RGS21, PLEK, and CCR9) in time to celiac disease analyses (10−4>P>5.8x10−6)." (PMID 27015091, 2016). "However, confirmatory evidence (p<10−4) was found for SNPs in five regions previously reported to be associated with celiac disease (TAGAP, IL18R1, RGS21, PLEK, and CCR9)." (PMID 27015091, 2016).
Insulin resistance (1 paper, 2022). Increased resistance towards insulin, that is, diminished effectiveness of insulin in reducing blood glucose levels. "Finally, the associations of RGS8, RGS13, RGS18, and RGS21 with insulin secretion or insulin resistance need to be further investigated." (PMID 36497154, 2022).
small cell lung carcinoma (1 paper, 2022). Small cell lung cancer (SCLC) is a highly aggressive malignant neoplasm, accounting for 10-15% of lung cancer cases, characterized byrapid growth, and early metastasis.
cancer (1 paper, 2022). A tumor composed of atypical neoplastic, often pleomorphic cells that invade other tissues. "Currently there is no published evidence that RGS21 is involved in cancer development." (PMID 35634240, 2022).
tumor (1 paper, 2022). "As a result, we found that ITPR1, ITPR2, and ITPR3 proteins may interact with tumor-promoting genes, such as PLCB1, PLCB2, PRKCA, and RGS21, which may partially explain its oncogene roles." (PMID 35580861, 2022).
RGS21 also shares sentences with these, for which no sentence is quoted: adenocarcinoma (1 paper).